Y_RNA (Y RNA )
Gene: Miscellaneous RNA gene on chromosome 12 (38,274,448 to 38,274,549, reverse strand). Ensembl gene ENSG00000253016.
Homologues: Orthologues: chimpanzee Y_RNA (99% identical), macaque Y_RNA (88% identical). Paralogues in human: Y_RNA (91% identical), Y_RNA (82% identical), Y_RNA (81% identical), Y_RNA (80% identical), RNY3 (79% identical), RNY3P1 (79% identical), Y_RNA (79% identical), RNY3P14 (78% identical), Y_RNA (78% identical), Y_RNA (77% identical), RNY3P16 (76% identical), Y_RNA (76% identical), and 93 more.